LEAP2 (liver enriched antimicrobial peptide 2)
Description:
Has an antimicrobial activity.
Synonyms: LEAP-2
Tractability: Antibody: its Gene Ontology location is reachable by antibodies, with high confidence; UniProt places it where antibodies can reach, with medium confidence; UniProt predicts a signal peptide or a membrane-spanning region.
Gene: Protein-coding gene on chromosome 5 (132,873,444 to 132,875,046, forward strand). Ensembl gene ENSG00000164406.
Subcellular location: Secreted
Pathways (Reactome):
Immune System: Antimicrobial peptides
Gene Ontology:
Biological process: defense response to bacterium
Cellular component: extracellular region
Genetic constraint (gnomAD): Loss-of-function variants: 13 observed, 9.92 expected, observed/expected ratio (o/e) 1.31, 90% interval 0.84 to 1.87. That is too few expected variants to judge how well the gene tolerates losing a copy. Missense variants: 98 observed, 99.48 expected, observed/expected ratio (o/e) 0.99, 90% interval 0.84 to 1.16. Synonymous variants: 34 observed, 37.15 expected, observed/expected ratio (o/e) 0.92, 90% interval 0.69 to 1.22.
Homologues: Orthologues: chimpanzee LEAP2 (100% identical), macaque LEAP2 (99% identical), dog LEAP2 (88% identical), rabbit LEAP2 (88% identical), mouse Leap2 (84% identical), guinea pig LEAP2 (83% identical), rat Leap2 (81% identical), pig LEAP2 (75% identical), tropical clawed frog leap2 (49% identical), zebrafish si:dkey-22f5.9 (38% identical).
Diseases named in the same sentence as LEAP2 in open-access papers:
LEAP2 is named in the same sentence as 60 diseases in open-access papers, as found by Europe PMC text mining. Sharing a sentence is not in itself a finding about the gene and the disease. The quoted sentences say what the papers report.
Obesity (33 papers, 2020 to 2026). Accumulation of substantial excess body fat. "Emerging evidence indicates that obesity and type 2 diabetes are generally associated with reduced circulating ghrelin levels and increased LEAP2 concentrations, particularly in the presence of insulin resistance." (PMID 42277455, 2026). "The present study aimed to determine serum LEAP2 levels in patients with insulinoma, assess their associations with obesity and obesity-related hormones, and examine LEAP2 peptide expression in insulinoma tissue." (PMID 41488138, 2025). "Another study proved that LEAP2 is associated with increased insulin secretion in adults with obesity and overweight." (PMID 39796232, 2025). "In conclusion, serum LEAP2 levels are significantly elevated in patients with insulinoma, closely associated with hyperinsulinemia, and possibly linked to obesity." (PMID 41488138, 2025). "LEAP-2 increases whereas ghrelin decreases in obesity, and LEAP-2 is implicated in obesity-related disorders, including polycystic ovary syndrome and non-alcoholic fatty liver disease." (PMID 41303478, 2025). "In another clinical trial that assessed a cohort with prediabetes and overweight/obesity, fasting plasma LEAP2 levels were inversely associated with insulin sensitivity and positively associated with BMI, body weight, and fat mass." (PMID 40214973, 2025). "In humans, weight loss after VSG and RYGB surgery for obesity reduced fasting and/or postprandial plasma LEAP2 at 3 to 24 months after 16% to 31% weight loss." (PMID 39659543, 2024). "Accordingly, circulating LEAP2 and acyl-ghrelin correlated negatively, and serum LEAP2 levels are elevated in obesity and decreased in energy-deficient states, which then allows the action of the acyl-ghrelin." (PMID 35187383, 2022). "A large volume of data show that human obesity is associated with higher plasma LEAP2 and lower plasma AG, similar to obesity in mice." (PMID 36235843, 2022). "In adults, obesity was associated with an increase in plasma LEAP2 levels and a decrease in plasma acyl ghrelin levels." (PMID 35521798, 2022). "Similar findings have been reported from studies with mice with decreased LEAP2 after diet-induced weight loss and increased LEAP2 after diet-induced obesity." (PMID 35187383, 2022). "In this review, we summarize recent findings in the properties of LEAP-2, analyze its association with obesity, and discuss the potential application and limits in anti-obesity." (PMID 34512549, 2021). "Obesity has been associated with increased LEAP2 levels and low ghrelin levels." (PMID 40870497, 2025). "In the future, LEAP2 could become an important agent in the development of treatments aimed at curbing obesity and its associated metabolic disorders." (PMID 39796232, 2025). "Just as an elevated LEAP2/ghrelin molar ratio has been proposed as a contributing factor to the ghrelin resistance associated with obesity, we now propose a “hippocampal ghrelin resistance” hypothesis of normal cognitive aging." (PMID 37212281, 2023). "Hence, LEAP2 concentrations have been reported to decrease during weight loss and increase with obesity." (PMID 35492241, 2022). "In addition, fasting plasma LEAP2 levels were positively correlated with obesity-associated metabolic indexes such as BMI, percentage of body fat, fasting blood glucose, and triglyceride levels." (PMID 35521798, 2022). "Although the detailed mechanism awaits further elucidation, developing novel strategies that target the upregulation of central LEAP2 expression might provide a promising approach to combat obesity and its associated diseases." (PMID 36387867, 2022). "Liver-expressed antimicrobial peptide 2 (LEAP2), a novel hormone and endogenous antagonist of the ghrelin receptor, is associated with obesity; however, its relationship with obesity and hyperinsulinemia in insulinoma, and its expression within tumor tissue, remains unknown." (PMID 41488138, 2025).
Obesity (continued). "However, the effects of long-term dietary caloric restriction for obesity causing weight loss on plasma LEAP2, and the potential metabolic mediators, are unknown in humans." (PMID 39659543, 2024). "The ghrelin-LEAP2 system represents a key regulatory pathway in metabolic homeostasis and a promising therapeutic target for obesity and related metabolic disorders." (PMID 42277455, 2026). "LEAP-2 is being investigated as a potential therapeutic target for obesity and related metabolic diseases, as it can impact food intake and body weight." (PMID 41303478, 2025). "Blood LEAP-2 concentrations have been reported to fluctuate in relation to obesity levels and obesity-related parameters." (PMID 41561064, 2025). "In patients with severe obesity-associated non-alcoholic fatty liver disease (NAFLD), LEAP-2 has been found to slightly induce the upregulation of factors involved in fibrogenesis such as α-SMA, COL1α1, and TIMP1 via the PI3K/Akt/mTOR signaling pathway." (PMID 39860298, 2025). "Further research is needed to better define the role of LEAP2 in ghrelin-mediated food intake and its potential as a therapeutic target in obesity." (PMID 40870497, 2025). "Ghrelin reverses the activation of fibrogenesis induced by LEAP-2, and ghrelin levels are inversely related to the severity of liver fibrosis in patients with severe obesity." (PMID 41226108, 2025). "Comparisons of obese and normal-weight individuals show that LEAP2 levels tend to increase in obesity in contrast to ghrelin." (PMID 40870497, 2025). "This provides insights into LEAP2 being used as a therapeutic agent for insulin secretion in type 2 diabetes and obesity as LEAP2 most likely directly increases insulin production rather than insulin sensitivity." (PMID 39796232, 2025). "LEAP-2 alone or the LEAP-2/ghrelin molar ratio showed potential as therapeutic targets for obesity, diabetes, and metabolic disorders." (PMID 39860298, 2025). "Many studies have recognized LEAP-2 as a potential therapeutic target for ghrelin-related diseases, including obesity, cachexia, diabetes, anorexia, alcohol abuse, and Prader–Willi syndrome." (PMID 41226108, 2025). "Articles such as have shown that RYGB, also known as one of the most efficient obesity and type 2 diabetes treatments, lowers the level of plasma LEAP2." (PMID 39796232, 2025). "In the first detailed study examining LEAP-2 regulation in humans, a clear link between LEAP-2 and human metabolic states such as BMI, obesity, and food intake was identified." (PMID 39860298, 2025). "This study was conducted to investigate the role of liver-enriched antimicrobial peptide-2 (LEAP2) in insulinoma, a unique human model of endogenous hyperinsulinemia and obesity." (PMID 41488138, 2025). "To conclude, the current state of knowledge pushes for the idea of LEAP2 having a benevolent influence on organisms suffering from diabetes and suffering from or developing obesity." (PMID 39796232, 2025). "Together with previous evidence, our findings support the concept that LEAP2 represents a promising therapeutic target for obesity." (PMID 41488138, 2025). "Dietary-induced weight loss with increased physical activity in participants with obesity and inadequately controlled T2DM caused fasting plasma LEAP2 decreases." (PMID 39659543, 2024). "In humans, weight loss after Roux-en-Y gastric bypass (RYGB) and vertical sleeve gastrectomy (VSG) surgery for obesity reduced fasting and/or postprandial plasma LEAP2." (PMID 39659543, 2024). "In humans, short-term 2-week LCD (1200 kcal/day) without and with interval exercise (60 minutes/day) in women with obesity lowered fasting plasma LEAP2, and this was likely due to caloric restriction and weight loss, since exercise had no additive effect." (PMID 39659543, 2024). "In the present study, postprandial plasma LEAP2 increased after a 600-kcal liquid meal at baseline in adults with obesity and T2DM, consistent with the previous literature." (PMID 39659543, 2024).
Obesity (continued). "In mice, peripheral and central LEAP2 administration antagonizes orexigenic effects of AG administration, and on its own reduces food intake, and a long-acting LEAP2 peptide reduces weight hepatic steatosis over four weeks in diet-induced obesity." (PMID 39659543, 2024). "Short-term, 2-week LCD also reduced fasting plasma LEAP2 in obesity, though plasma LEAP2 tended to increase post glucose ingestion." (PMID 39659543, 2024). "LEAP-2 (Liver-expressed antimicrobial peptide 2) has been characterized as an endogenous competitive antagonist of ghrelin and proposed as a potential therapeutic target for obesity." (PMID 38161982, 2023). "Postprandial increases in plasma LEAP2 were also positively correlated with body mass index (BMI) across a combined group of adults with normal weight and obesity." (PMID 37287649, 2023). "This viewpoint is reinforced by a paper that showed improvements in obesity and diabetes when levels of acyl ghrelin were reduced, levels of Leap2 were increased, or GHSR activity was blocked." (PMID 36936164, 2023). "Of note, the anorexigenic effect of LEAP-2 observed in mice exposed to HFD is in contrast to the leptin resistance usually observed in diet induced obesity." (PMID 35159134, 2022). "Taken together from these data LEAP-2 emerged as a potential candidate to be therapeutically useful in obesity." (PMID 35159134, 2022). "Secretion of LEAP2 depends on the metabolic state of the body being increased in obesity and reduced in fasting." (PMID 35050161, 2022). "It has been suggested that LEAP2 is regulated in a manner diametrically opposite to that of ghrelin, and that increased levels of LEAP2 in the state of obesity contributes to ghrelin resistance." (PMID 35050161, 2022). "The aetiology of obesity remains complex and incompletely understood, although studies have reported reduced levels of ghrelin and increased LEAP-2 in obese mouse models and human patients." (PMID 35203552, 2022). "This view is supported by a report that obesity and diabetes were improved by reducing acyl ghrelin levels, increasing LEAP2 levels, or blocking GHSR activity." (PMID 35521798, 2022). "Both animal models of obesity showed higher levels of LEAP-2 in circulation in comparison to their lean controls." (PMID 35159134, 2022). "Although LEAP-2 level is upregulated during obesity, this increase seems to be unsatisfactory to suppress appetite and adiposity because it does not stop people from gaining weight." (PMID 34512549, 2021). "Then, we analyzed the potential links between LEAP-2 and obesity to facilitate future research on the treatment of obesity based on LEAP-2." (PMID 34512549, 2021). "Perhaps this persistently high LEAP2 was still able to prevent the elevated ghrelin in GhIRKO mice from exerting its metabolic effect in the setting of diet-induced obesity." (PMID 34473648, 2021). "We further analyzed the secretion data of LEAP-2 relative to energy balance and examined its implication to metabolic disorders, especially obesity." (PMID 34512549, 2021). "Given LEAP-2 is dramatically upregulated under obesity, it is highly likely to play a prominent role in reducing GH levels." (PMID 34512549, 2021). "Among the pathways proposed to mediate the ghrelin resistance of obesity is a coordinated rise in plasma LEAP2 and a fall in plasma ghrelin observed in both humans and mice with obesity." (PMID 34473648, 2021). "In this review, we will analyze LEAP-2’s effects from a metabolic point of view with a focus on metabolic hormones (e.g., ghrelin, GH, and insulin), and discuss LEAP-2’s potential as a promising therapeutic target for obesity." (PMID 34512549, 2021). "This discovery led to the proposal of LEAP2 as a new potential therapeutic target for uncontrolled ghrelin signaling-related diseases, such as obesity and diabetes, cachexia, anorexia, alcohol abuse, and Prader-Willi Syndrome." (PMID 35011234, 2021).
Obesity (continued). "Inhibiting ghrelin’s activity has shown beneficial effects on obesity in preclinical experiments, which sheds light on LEAP-2’s anti-obesity potential." (PMID 34512549, 2021). "High concentration of circulating LEAP-2 during obesity prevents ghrelin binding to GHS-R1a and contributes to the so called ghrelin resistant phenomenon observed in diet-induced obese (DIO) mice." (PMID 34512549, 2021). "Due to its effect on suppressing appetite, LEAP-2 has potential to be developed as an anti-obesity drug." (PMID 34512549, 2021). "In high fat diet-induced obese mice, vertical sleeve gastrectomy, a common surgery for the treatment of obesity, resulted in increased expression of Leap2 in the stomach and decreased expression in the duodenum." (PMID 31539874, 2020). "LEAP2 agonism represents a possible therapeutic target for obesity and diabetes, and LEAP2 antagonism for anorexia and cancer cachexia." (PMID 31539874, 2020). "In this review, we summarize the evolutionary diversity and functional characteristics of LEAP-2 across species, analyze its therapeutic potential in treating obesity, diabetes, addiction, and other diseases, and explore its potential clinical applications and limitations." (PMID 39860298, 2025). "Our results also highlight the relationship between LEAP2 and obesity." (PMID 41488138, 2025). "LEAP-2 has emerged as a promising therapeutic candidate for treating obesity." (PMID 41226108, 2025). "This suggests that LEAP2 could have potential not only as a therapeutic agent for obesity and diabetes but also in the treatment of PCOS or as a biomarker for this condition." (PMID 39796232, 2025). "It has been reported that LEAP2 is upregulated in the state of positive energy balance in obesity and diabetes; this may be a counter-regulatory mechanism to prevent a further increase in energy stores." (PMID 40870497, 2025). "Materials and Methods: We conducted a narrative review of human and animal studies published in the literature investigating the roles of acyl ghrelin, des-acyl ghrelin, and LEAP2 in food intake regulation, as well as changes in their levels in obesity and following bariatric surgery." (PMID 40870497, 2025). "Additional modulation may involve liver-expressed antimicrobial peptide 2 (LEAP-2), which could exacerbate ghrelin resistance due to its association with obesity and metabolic syndrome, both recognized AD risk factors." (PMID 41303478, 2025). "LEAP2 has been reported to be a promising therapeutic target for obesity and other metabolic diseases, with the view that further increasing the LEAP2–ghrelin molar ratio may help restrict food intake." (PMID 40870497, 2025). "Strengths of this study include the concomitant measurement of three appetite- and obesity-related hormones, the use of validated antibodies to confirm LEAP2 expression, and a relatively large patient cohort for a rare tumor, which enabled meaningful analyses in this distinctive disease model." (PMID 41488138, 2025). "Just like mice, obese humans also show increases in plasma LEAP2 and the LEAP2/acyl-ghrelin molar ratio; therefore, LEAP2 also positively correlates with some metabolic parameters connected to obesity such as the BMI, HOMA-IR, VAT volume, and serum triglycerides." (PMID 39796232, 2025). "LEAP2 is primarily secreted by the liver and increases with greater body mass and insulin resistance in individuals with prediabetes and overweight or obesity; therefore, an elevated LEAP2 level might indicate increased metabolic risk." (PMID 38898508, 2024). "The effects of dietary-induced weight loss on fasting and plasma LEAP2 will also need to be assessed in people with obesity without T2DM and well-controlled T2DM." (PMID 39659543, 2024). "In men without obesity, 60 minutes’ endurance exercise reaching 70% maximal oxygen consumption lowered fasting plasma LEAP2, associated with increases in plasma ketone β-hydroxybutyrate." (PMID 39659543, 2024).